IGHV1OR15-9 (immunoglobulin heavy variable 1/OR15-9 (non-functional))
Synonyms: IGHV1/OR15-9; IGHV1OR159; VSIG7
Gene: Immunoglobulin variable (V) gene on chromosome 15 (19,964,666 to 19,965,101, reverse strand). Ensembl gene ENSG00000188403.
Gene Ontology:
Molecular function: antigen binding
Biological process: immunoglobulin mediated immune response
Cellular component: extracellular region; plasma membrane
Homologues: Orthologues: mouse Ighv1-50 (66% identical), mouse Ighv1-69 (65% identical), mouse Ighv1-64 (64% identical), mouse Ighv1-74 (64% identical), mouse Ighv1-52 (63% identical), mouse Ighv1-53 (63% identical), mouse Ighv1-59 (63% identical), mouse Ighv1-85 (63% identical), mouse Ighv1-26 (62% identical), mouse Ighv1-36 (62% identical), mouse Ighv1-55 (62% identical), mouse Ighv1-61 (62% identical), and 47 more. Paralogues in human: IGHV1OR21-1 (91% identical), IGHV1-3 (78% identical), IGHV1-46 (78% identical), IGHV1-2 (76% identical), IGHV1OR15-1 (75% identical), IGHV1-69-2 (74% identical), IGHV1-18 (73% identical), IGHV1-45 (73% identical), IGHV1-24 (72% identical), IGHV1-69 (72% identical), IGHV1-69D (72% identical), IGHV1-58 (68% identical), and 65 more.